SH3PXD2A (SH3 and PX domains 2A)
Description:
Adapter protein involved in invadopodia and podosome formation, extracellular matrix degradation and invasiveness of some cancer cells. Binds matrix metalloproteinases (ADAMs), NADPH oxidases (NOXs) and phosphoinositides. Acts as an organizer protein that allows NOX1- or NOX3-dependent reactive oxygen species (ROS) generation and ROS localization. In association with ADAM12, mediates the neurotoxic effect of amyloid-beta peptide.
Synonyms: FISH; KIAA0418; SH3MD1; TKS5
Tractability: PROTAC: ubiquitination databases record sites on it; its protein half-life has been measured.
Gene: Protein-coding gene on chromosome 10 (103,594,027 to 103,855,584, reverse strand). Ensembl gene ENSG00000107957.
Subcellular location: Cytoplasm; Cell projection, podosome
Subcellular location (Human Protein Atlas): Cytosol; Primary cilium transition zone
Pathways (Reactome):
Extracellular matrix organization: Invadopodia formation
Signal Transduction: CDC42 GTPase cycle
Gene Ontology:
Molecular function: protein binding; superoxide-generating NADPH oxidase activator activity; phosphatidylinositol binding
Biological process: osteoclast fusion; superoxide metabolic process; superoxide anion generation
Cellular component: podosome; cytoplasm; cytosol
Genetic constraint (gnomAD): Loss-of-function variants: 25 observed, 92.87 expected, observed/expected ratio (o/e) 0.27, 90% interval 0.19 to 0.38. The upper end of that interval is the gene's LOEUF score, 0.38, which puts it in group 1 of 6, group 1 being the genes least tolerant of losing a copy. Missense variants: 1,221 observed, 1,401.4 expected, observed/expected ratio (o/e) 0.87, 90% interval 0.83 to 0.91. Synonymous variants: 558 observed, 599.05 expected, observed/expected ratio (o/e) 0.93, 90% interval 0.87 to 1.
Homologues: Orthologues: chimpanzee SH3PXD2A (99% identical), macaque SH3PXD2A (97% identical), pig SH3PXD2A (94% identical), dog SH3PXD2A (93% identical), rabbit SH3PXD2A (91% identical), rat Sh3pxd2a (91% identical), mouse Sh3pxd2a (91% identical), guinea pig SH3PXD2A (91% identical), tropical clawed frog sh3pxd2a (69% identical), zebrafish sh3pxd2aa (56% identical), zebrafish sh3pxd2ab (34% identical). Paralogues in human: SH3PXD2B (34% identical), NCF1 (12% identical), NOXO1 (7% identical).
Diseases named in the same sentence as SH3PXD2A in open-access papers:
SH3PXD2A is named in the same sentence as 58 diseases in open-access papers, as found by Europe PMC text mining. Sharing a sentence is not in itself a finding about the gene and the disease. The quoted sentences say what the papers report.
breast carcinoma (23 papers, 2008 to 2025). "In another study on breast cancer, novel validated targets of miR-200c, SH3 and PX domains 2A (TKS5), and myosin light chain kinase (MYLK) were downregulated by miR-200c through the ZEB1 pathway." (PMID 27601996, 2016). "Other genes we replicated have been reported to play a role in breast cancer progression such as HOXD9, TDRD10, SH3PXD2A and TSPAN15, although these studies did not involve DNA methylation data as a prognostic marker." (PMID 39825380, 2025).
prostate carcinoma (8 papers, 2015 to 2022). A carcinoma that arises from epithelial cells of the prostate gland. "The SH3PXD2A gene was expressed at higher levels in lung, colon, breast and prostate cancer tissues than in normal tissues." (PMID 35410446, 2022).
lung adenocarcinoma (6 papers, 2015 to 2021). A carcinoma that arises from the lung and is characterized by the presence of malignant glandular epithelial cells. "SH3PXD2A’s increased expression in lung adenocarcinoma directly correlated with metastasis and worse prognosis for the patient." (PMID 34262872, 2021).
lung carcinoma (5 papers, 2015 to 2025). "While the involvement of SH3PXD2A in cisplatin resistance has not been reported in ESCC, it has been associated with cisplatin resistance in non‐small cell lung cancer." (PMID 40923294, 2025).
pulmonary fibrosis (4 papers, 2023 to 2026). Chronic progressive interstitial lung disorder characterized by the replacement of the lung tissue by connective tissue, leading to progressive dyspnea, respiratory failure, or right heart failure. "To enable functional studies on the likely role of Tks5 in pulmonary fibrosis and pathophysiology in mice, we then created a series of obligatory and conditional knock out mice for Tks5 (Sh3pxd2a)." (PMID 37735172, 2023).
glioma (3 papers, 2021 to 2023). A benign or malignant brain and spinal cord tumor that arises from glial cells (astrocytes, oligodendrocytes, ependymal cells). "To further confirm these results, we evaluated the expression levels of SH3PXD2B, SH3PXD2A and EFHD2 mRNAs and encoded proteins in IDH-wt glioma cells (U87MG and T98G) overexpressing miR-1, miR-26a-1 and miR-487b, respectively." (PMID 36932446, 2023).
rosacea (3 papers, 2023 to 2026). A chronic erythematous skin disorder that affects the face. "The relevance of SH3PXD2A, SLC26A8 and LRR family genes in rosacea predisposition is underscored by presence of additional variants in independent families." (PMID 37402769, 2023). "Collectively, these data further highlight SH3PXD2A, SLC26A8 and LRR family genes as potential candidate genes for rosacea susceptibility." (PMID 37402769, 2023). "In the present study, based on WGS of 3 large rosacea families (as discovery cohort) and WES of 49 additional small rosacea families (as validation cohort), we identified LRRC4, SH3PXD2A, and SLC26A8, each with a single rare genetic variant, as potential candidate genes for rosacea susceptibility." (PMID 37402769, 2023). "Furthermore, through whole‐genome sequencing, researchers identified three genes—LRRC4, SH3PXD2A, and SLC26A8—each of which has rare genetic variations associated with susceptibility to rosacea within families, indicating these genes as potential susceptibility genes." (PMID 41437844, 2026).
Stroke (3 papers, 2021 to 2024). Sudden impairment of blood flow to a part of the brain due to occlusion or rupture of an artery to the brain. "SH3PXD2A is associated with brain white matter lesions and stroke." (PMID 39228919, 2024). "These loci provide insights into lacunar stroke pathogenesis, highlighting disruption of the vascular extracellular matrix (COL4A2, LOX, SH3PXD2A, GPR126, HTRA1), pericyte differentiation (FOXF2, GPR126), TGF-β signalling (HTRA1), and myelination (ULK4, GPR126) in disease risk." (PMID 33773637, 2021).
Alzheimer disease (2 papers, 2020 to 2024). A progressive, neurodegenerative disease characterized by loss of function and death of nerve cells in several areas of the brain leading to loss of cognitive function such as memory and language. "Interestingly, rs3740473 of SH3PXD2A is associated with Alzheimer’s disease." (PMID 39228919, 2024).
orofacial clefting (2 papers, 2019 to 2022). "Observations in zebrafish and knockout mice suggest that SH3PXD2A is also a potential risk gene for orofacial clefting." (PMID 31817908, 2019).
ovarian carcinoma (2 papers, 2020 to 2024). A malignant neoplasm originating from the surface ovarian epithelium. "SH3PXD2A forms a complex with ULK1 and MTOR, and the ULK1-SH3PXD2a-MMP14 axis upregulates the aggressiveness of ovarian cancer." (PMID 38903532, 2024).
bipolar disorder (1 paper, 2024). A disorder of the brain that causes unusual shifts in mood, energy, activity levels and the ability to carry out day-to-day tasks. "In conclusion, CACNA1C, GABBR2, SCN2A, CTSH, MSRA, and SH3PXD2A may be associated with the neuro-progression of bipolar disorder to dementia." (PMID 39228919, 2024). "In conclusion, the genes CACNA1C, GABBR2, SCN2A, CTSH, MSRA, and SH3PXD2A may be associated with the neuro-progression of bipolar disorder to dementia." (PMID 39228919, 2024). "The mechanism by which SH3PXD2A is linked to bipolar disorder remains unknown; however, a GWAS revealed a significant association between bipolar disorder and SH3PXD2A." (PMID 39228919, 2024). "The results showed that the genes CACNA1C, GABBR2, SCN2A, CTSH, MSRA, and SH3PXD2A were overlapping between patients with bipolar disorder and dementia." (PMID 39228919, 2024). "According to GWAS, the CACNA1C, GABBR2, SCN2A, CTSH, MSRA, and SH3PXD2A genes were common between bipolar disorder and dementia." (PMID 39228919, 2024). "Therefore, SH3PXD2A is a gene of interest in relation to bipolar disorder and dementia." (PMID 39228919, 2024).
cerebral small vessel disease (1 paper, 2021). Cerebral small vessel disease is the term currently used to pathological processes that affect the brain parenchymal circulation (arterioles, capillaries, and veins). "Disruption of the vascular ECM has been hypothesised to be a key component in pathogenesis of cerebral small vessel disease, particularly in monogenic forms, and several of the genes implicated in this study (COL4A2, LOX, SH3PXD2A, GPR126, HTRA1) have key roles in the ECM." (PMID 33773637, 2021).
cleft lip (1 paper, 2024). Congenital defect in the upper lip where the maxillary prominence fails to merge with the merged medial nasal prominences. "This study utilized GS to investigate a potential gene (SH3PXD2A) associated with cleft lip." (PMID 38233799, 2024).
conduction disorders (1 paper, 2026). "However, LDSC and TSMR analyses in our study did not demonstrate that SH3PXD2A was a significant predictor of conduction disorders." (PMID 41541644, 2026).
preeclampsia (1 paper, 2024). Preeclampsia is a hypertensive disorder of pregnancy that is characterized by new-onset hypertension with proteinuria presenting after 20 weeks of gestation, and depending on mild or severe forms may initially present with severe headache, visual disturbances, and hyperreflexia. "SH3PXD2A has been previously reported to be potentially involved in the pathogenesis of preeclampsia and trophoblast function." (PMID 39438452, 2024).
systemic sclerosis (1 paper, 2024). A chronic disorder, possibly autoimmune, marked by excessive production of collagen which results in hardening and thickening of body tissues. "Tenascin C was recently shown to be highly upregulated in systemic sclerosis and to be associated with fibrosis, while SH3PXD2A (formerly TKS5) is involved in extracellular matrix degradation in both normal podosomes/invadopodia and in cancer cells." (PMID 39112965, 2024).
vascular dementia (1 paper, 2024). A degenerative vascular disorder affecting the brain. "It is noteworthy that SH3PXD2A (rs17738042) is significantly associated with vascular dementia." (PMID 39228919, 2024).
cancer (49 papers, 2011 to 2026). A tumor composed of atypical neoplastic, often pleomorphic cells that invade other tissues. "Tks-5, encoded by the SH3PXD2A gene, is also essential for invadopodia formation in cancer cells, interacting with proteins like Wiskott–Aldrich syndrome protein (N-WASP) and cortactin, which are involved in actin remodeling." (PMID 39941035, 2025). "Both the cancer migration pathway and deregulation of the actin cytoskeleton can be related to downregulation of SH3PXD2A after miR‐218 overexpression." (PMID 35702951, 2022). "TKS5 (Tyrosine kinase substrate with five SH3 domains - SH3PXD2A) is essential for invadopodia formation in cancer cells." (PMID 26334100, 2015). "Due to the dysregulation of SH3PXD2A gene expression has been shown in many diverse cancers, lncRNA generation in the SH3PXD2A genes may play important roles in tumorigenesis." (PMID 35410446, 2022). "Since SH3PXD2A or CCR7 are reported to be involved cancer cell invasion and migration, downregulation of CTCF targets SH3PXD2A and CCR7 by SH3PXD2A-AS1 might have similar functional effects on trophoblast cells during placentation." (PMID 32719429, 2020). "SH3PXD2A and STX18 promote or inhibit the development of other cancers, consistent with our prognostic model." (PMID 38903532, 2024). "The Src substrate tyrosine kinase substrate 5 (Tks5, also known as SH3PXD2A) is an adaptor protein that was observed to regulate ECM remodeling via the modulation of specialized adhesion structures called “podosomes” in normal cell types and “invadopodia” in cancer cells." (PMID 36471888, 2022).
tumor (40 papers, 2011 to 2026). "Together, these results show that invadosome disruption (by SH3PXD2A or CAV1 KD) consequently impacts the ability of tumour cells to remodel the environing collagen network." (PMID 37903910, 2023). "The screening of the GEPIA database revealed that CLIP2 and SH3PXD2A displayed substantial differences in expression between tumour and normal specimens in OC." (PMID 36131789, 2022). "Among the inactive NBC-hom-related genes, we want to highlight the presence of proteins involved in interactions with the microenvironment, such as ADAM12, ITGA7, SH3PXD2A, and TNXB, since the tumor microenvironment is known to play a key role in MCL growth and therapy resistance." (PMID 41524027, 2026).
SH3PXD2A also shares sentences with these, for which no sentence is quoted: melanoma (11 papers); breast tumor (4); pancreatic cancer (3); bladder cancer (2); brain tumors (2); colon cancer (2); lymph node metastasis (2); pancreatic adenocarcinoma (2); schwannoma (2); ameloblastoma (1); B cell lymphomas (1); Bardet-Biedl syndrome type 13 (1); bladder tumour (1); breast adenocarcinoma (1); cholangiocarcinoma (1); dementia (1); ectodermal dysplasia (1); fibrosarcoma (1); Frank-Ter Haar syndrome (1); gastric cancer (1); glioblastoma (1); idiopathic pulmonary fibrosis (1); infection (1); invasive breast carcinoma (1); late-onset Alzheimers disease (1); lymphoma (1); malignant peripheral nerve sheath tumor (1); Meckel syndrome, type 1 (1); metastatic cancers (1); metastatic melanoma (1).
A further 8 diseases each share a sentence with SH3PXD2A in 1 paper.